MCL1 (MCL1 apoptosis regulator, BCL2 family member)
Diseases named in the same sentence as MCL1 in open-access papers (continued):
Sharing a sentence is not in itself a finding about the gene and the disease.
glioblastoma (63 papers, 2013 to 2025). The most malignant astrocytic tumor (WHO grade IV). "Based on these data, we used shRNAs targeting BCL2, Bcl-xL, and MCL-1 anti-apoptotic proteins in stably P21-overexpressing senescent glioblastoma cells, as compared to naïve cells or cells deficient in P21." (PMID 36831620, 2023). "In this report, we demonstrate that inhibition of Bcl-xL causes synthetic lethality in IDH1-mutated glioblastoma cells in vitro and in vivo and that these effects are mediated by the oncometabolite, 2-HG, which reduces Mcl-1 protein levels." (PMID 29057925, 2017). "U87MG and murine glioblastoma cells bearing the IDH1 mutation showed decreased expression of Mcl-1, Bcl-xL, and Bcl-2." (PMID 29057925, 2017). "Based on our observation that in IDH1-mutated glioblastoma cells Mcl-1 expression is decreased, we next examined whether 2-HG treatment would recapitulate this molecular feature." (PMID 29057925, 2017). "Researchers have designed acid-sensitive bionic nanocarriers based on ApoE peptide-modified erythrocyte membranes for the delivery of Bcl-2/Bcl-xl and Mcl-1 inhibitors to treat glioblastoma (GBM)." (PMID 40420216, 2025). "The present study is the first to report that PD induces both apoptosis and autophagy by targeting LC3/MCL-1 in glioblastoma cells both in vitro and in vivo." (PMID 41049425, 2025). "In summary, PD induces both apoptosis and autophagy in glioblastoma cells through LC3B/MCL-1 modulation, demonstrating strong antitumor potential against human glioblastoma." (PMID 41049425, 2025). "Western blot analysis revealed that PD significantly reduced MCL-1 protein expression in both glioblastoma cell lines." (PMID 41049425, 2025). "Based on the role of MCL-1 in glioblastoma development, we used a series of computer-aided techniques to screen safer and more effective MCL-1 small molecule inhibitors from the ZINC15 database." (PMID 37538176, 2023). "This study demonstrated that MCL-1 was a key factor affecting the prognosis of glioblastoma patients, and inhibition of MCL-1 can improve the prognosis of glioblastoma patients." (PMID 37538176, 2023). "Glioblastoma cell lines such as U251 and u87 when treated with miR-342 resulted in the reduction in the expression of anti-apoptotic genes Bcl2-L1 and Mcl-1." (PMID 37736508, 2023). "We used lasso cox regression analysis to construct an MCL-1 related prognostic evaluation model and prognostic-related nomogram to predict the survival rate of glioblastoma patients." (PMID 37538176, 2023). "Numerous previous studies have demonstrated that MCL-1 is extremely important for glioblastoma, which can be used as a key target to inhibit the activity of glioblastoma cells." (PMID 37538176, 2023). "4-phenylbutyric acid, 5-aza-2 ́-deoxycytidine and Olea europaea leaf extract induce apoptosis through upregulation of miR-153 targeting Bcl-2, Mcl-1 and Irs2 in glioblastoma." (PMID 36158686, 2022). "Another example is miR-29b, which targets DNMT3b and MCL1 and is remarkably downregulated in lung, prostate, bladder, and ovarian cancers, as well as glioblastomas." (PMID 34199020, 2021). "In contrast to Mcl-1, the expression of Noxa was markedly more stable in glioblastoma cells treated with ABT-263 and PDT when compared to cells treated with solvent." (PMID 34439278, 2021). "In conclusion, we have demonstrated the significant anti-apoptotic effect of KRIBB11 on glioblastoma cells, which is associated with MULE-dependent destabilization of MCL-1." (PMID 34299435, 2021). "As previously discussed (see Section 3.1), zotiraciclib decreased transcription of the anti-apoptotic proteins MCL-1 and Survivin in glioblastoma cells, resulting in apoptosis." (PMID 34207158, 2021). "Although inhibition of Mcl-1 has received certain attention as a potential drug target, only slowly implemented in clinical applications and poses challenges in glioblastoma treatment due to high molecular weight and the blood brain barrier." (PMID 34485282, 2021).
glioblastoma (continued). "Treatment of glioblastoma cells with simvastatin or lovastatin also produced a consistent decrease in c-Myc, Mcl-1, Bcl-2, and Bcl-xL levels." (PMID 34209035, 2021). "Here, we demonstrated that glioblastomas harbor a super-enhancer at the MCL1 locus, which translated to increase MCL1 levels as compared to normal brain tissue." (PMID 32752193, 2020). "Gamitrinib-TPP is a mitochondrial HSP90 inhibitor and can induce MCL1 degradation in glioblastoma cells." (PMID 32484436, 2020). "In fact, the PIK3 inhibitor GDC-0941 has been shown to inhibit AKT phosphorylation of BAD, decrease MCL-1 expression, and inhibit the growth of glioblastoma cells in synergy with ABT-263." (PMID 31150457, 2019). "Anti-apoptotic proteins like Bcl-2, Bcl-xL, and Mcl-1 are often overexpressed in glioblastoma, allowing cellular proliferation and the resistance of tumor cells to various therapies." (PMID 30486451, 2018). "In the context of glioblastoma, public databases suggest that Mcl-1 is up-regulated in these tumors as compared to normal brain tissue." (PMID 30337641, 2018). "Addition of D-2HG to GBM cell cultures reduced the Mcl-1 expression and sensitized the glioblastomas to Bcl-XL inhibition both in vitro and in intracranial xenografts." (PMID 29439493, 2018). "In recurring glioblastomas, an overexpression of Bcl-2, Bcl-xL, and Mcl-1, and a downregulation of pro-apoptotic proteins like Bax, Bak, Bok, and NOXA have been observed." (PMID 30486451, 2018). "U87MG and LN229 glioblastoma cells silenced for Mcl-1 by four different siRNAs showed a marked increase in the fraction of sub-G1 cells when treated with ABT263." (PMID 29057925, 2017). "Therapies that target Mcl-1 are considered to be valuable in view of the fact that many tumors, including glioblastomas, display high levels of Mcl-1." (PMID 28415755, 2017). "We found here that pharmacological c-myc inhibition by JQ1 decreases Mcl-1 protein levels in multiple glioblastoma cell cultures, including patient derived xenograft cells." (PMID 28418907, 2017). "Anaplastic astrocytoma samples with mutated IDH1 display lower levels of Mcl-1 than IDH1 wild-type tumors and specific knockdown of Mcl-1 broadly sensitizes glioblastoma cells to Bcl-xL inhibition-mediated apoptosis." (PMID 29057925, 2017). "To further assess by which mechanism Mcl-1 is down-regulated, we performed real-time PCR analysis in T98G glioblastoma cells." (PMID 27172899, 2016). "Correlating Mcl-1 and USP9x expressions were significantly higher in human glioblastoma than in astrocytoma." (PMID 26775694, 2016). "Mcl-1 contributes to the neutralizing capacity, as downregulation of Mcl-1 sensitized all four glioblastoma cells to ABT737-induced apoptosis." (PMID 26775694, 2016). "Immunohistochemical analysis shows that number of Mcl-1- and USP9x-positive cells and staining intensity were significantly upregulated in glioblastoma compared with astrocytoma." (PMID 26775694, 2016). "The protein levels of USP9x and Mcl-1 were slightly but insignificantly higher in five of six glioblastoma cell lines than in Jurkat cells." (PMID 26775694, 2016). "Here, we used four established glioblastoma cell lines and two primary glioblastoma cell lines that express the antiapoptotic proteins Bcl-2, Bcl-xL, and Mcl-1, but showed different sensitivity to IR-induced apoptosis." (PMID 26775694, 2016). "All four glioblastoma cell lines expressed USP9x as well as antiapoptotic Mcl-1, Bcl-2, Bcl-xL, and pro-apoptotic Bax, Bak, Noxa, Puma, and Bad." (PMID 26775694, 2016). "Summarized, our results suggest that Mcl-1 stability is regulated by different mechanisms in irradiated A172 and U373 glioblastoma cells." (PMID 26775694, 2016). "SiRNA-mediated knock-down of Mcl-1 enhanced apoptosis induced by ABT263 in T98G glioblastoma cells and thereby phenocopied the sensitizing effect of L-asparaginase on ABT263." (PMID 27172899, 2016).
glioblastoma (continued). "This again implicates that other factors are also important regulators of Mcl-1 levels in glioblastoma tumors." (PMID 26775694, 2016). "Yet, Mcl-1 and USP9x IRS correlated moderately but significantly in grade IV glioblastoma (Spearman correlation, ρ=0.47, P=0.0063), indicating a coincidental upregulation of Mcl-1 and USP9x." (PMID 26775694, 2016). "We conclude that USP9x can control survival and radiosensitivity in glioblastoma cells by Mcl-1-dependent and Mcl-1-independent mechanisms." (PMID 26775694, 2016). "In the present study, we aimed to analyze the impact of USP9x on Mcl-1 and cell survival in glioblastoma cell lines." (PMID 26775694, 2016). "As expected, Mcl-1 knockdown sensitized all four glioblastoma cell lines to ABT737-induced apoptosis." (PMID 26775694, 2016). "Taken together, downregulation of Mcl-1 in response to IR is an important step in IR-induced apoptosis in glioblastoma cells." (PMID 26775694, 2016). "Our data confirms the previous notion that knocking down Usp9X suppresses Mcl-1 along with Bcl-2 and primes glioblastoma cells to ABT263." (PMID 26474387, 2015). "The antiapoptotic Bcl-2 family protein Mcl-1 is overexpressed in glioblastoma and represents an important resistance factor to the BH-3 mimetic ABT263." (PMID 26008975, 2015). "Our results show that knock-down of both Bag3 and Usp9X leads to a depletion of Mcl-1 protein levels in glioblastoma cells and rendered them highly sensitive to ABT263." (PMID 26008975, 2015). "Consistently, siRNA-mediated knock-down of Bag3 significantly reduced Mcl-1 levels and sensitized T98G glioblastoma cells to ABT263." (PMID 26474387, 2015). "Our findings suggested that in glioblastoma cells there is a marked increase of Mcl-1 mRNA levels in response to increasing concentrations of GX15-070." (PMID 26008975, 2015). "As increased autophagy and apoptosis were observed in both the combination and triple treatment, we related these effects to altered levels of the anti-apoptotic Bcl-2 proteins Bcl-XL and Mcl-1 in the patient-derived glioblastoma culture GS257." (PMID 25568669, 2014). "MCL-1 plays a critical role in the survival of glioblastoma cells by regulating apoptotic pathways." (PMID 41049425, 2025). "ELK4-mediated Mcl-1 overexpression promotes oncogenesis in glioblastoma." (PMID 41502523, 2025). "Elevated MCL-1 expression correlates with a poor prognosis in glioblastoma patients." (PMID 41049425, 2025). "Additionally, TCGA database analysis using TIMER 2.0 indicated that MCL-1 expression is significantly higher in glioblastoma tumor tissues (n =153) than in normal tissues (n=5)." (PMID 41049425, 2025). "Importantly, inhibitors of Bcl-2/Bcl-xl along with Mcl-1 inhibitors in a nanoparticle format has shown efficacy in animal model system in crossing the blood-brain barrier and suppressing the growth of glioblastoma." (PMID 39833890, 2025). "Inhibition of MCL-1 has been shown to increase the sensitivity of glioblastoma cells to chemotherapy and radiotherapy, suggesting that the targeting of MCL-1 could be an effective strategy for treating glioblastoma." (PMID 41049425, 2025). "However, we currently lack direct experimental evidence to confirm the role of MCL-1 in PD-induced mitochondrial apoptotic pathways in glioblastoma cells, which warrants further investigation." (PMID 41049425, 2025). "In order to examine whether the protein stability of Mcl-1 or Bcl-2 is affected, glioblastoma cells were treated with cycloheximide in the presence or absence of the dual treatment." (PMID 38396172, 2024). "The study’s findings are summarized in a list of potential MCL-1 small molecule inhibitors and their pharmacological characteristics, which can support and assist the research on MCL-1 inhibitors and give further leads for the creation and advancement of glioblastoma therapy medications." (PMID 37538176, 2023).
glioblastoma (continued). "Therefore, there is great potential for the development of MCL-1 specific inhibitors for the treatment of glioblastoma, and it is crucial to create inhibitors that are both more efficient and less poisonous for the treatment of glioblastoma." (PMID 37538176, 2023). "Therefore, a more suitable small-molecule MCL-1 inhibitor is required for the treatment of glioblastoma." (PMID 37538176, 2023). "However, our study did demonstrate that they can effectively inhibit the MCL-1 function, which provides more prodrugs for the treatment of glioblastoma." (PMID 37538176, 2023). "Additionally, the anti-apoptotic Bcl-2 family member myeloid cell leukemia factor-1 (Mcl-1), which interferes in early cascade events by suppressing cytochrome c release from mitochondria, is highly expressed in human glioblastoma." (PMID 34485282, 2021). "Indeed, in certain glioblastoma cell lines, it has been demonstrated that USP9X loss regulates radiosensitivity by Mcl-1-independent mechanisms." (PMID 34277417, 2021). "Indeed, an earlier in vitro study examined PTEN-mutated glioblastoma cell lines and demonstrated that co-inhibition of PI3K and Bcl-1 significantly depleted pAKT and Mcl-1 protein levels and enhanced cell apoptosis." (PMID 33747896, 2020). "In glioblastoma, downregulation of Mcl-1 by ONC201 was shown to be mediated posttranslationally." (PMID 33144917, 2020). "Indeed, STAT3 is a major actor of cell survival after therapy by regulating the expression of anti-apoptotic genes such as Bcl-xL or Mcl-1 in glioblastoma." (PMID 29423098, 2018). "Anti-apoptotic Bcl-2 family members, such as Bcl-xL and Mcl-1, are highly expressed in human glioblastomas and, therefore, it is conceivable that interference with these molecules might exert significant anti-glioblastoma activity." (PMID 29057925, 2017). "Maintaining high Mcl-1 levels seemed to be important for all glioblastoma cells." (PMID 26775694, 2016). "Downregulation of Mcl-1 correlated with apoptosis induction in established glioblastoma cell lines." (PMID 26775694, 2016). "Here we analyzed the impact of USP9x on Mcl-1 levels and radiosensitivity in glioblastoma cells." (PMID 26775694, 2016). "The data suggest that lowered Mcl-1 levels could sensitize the glioblastoma cells to IR-induced apoptosis or, in case of U373 cells, accelerate IR-induced apoptosis." (PMID 26775694, 2016). "Given that L-asparaginase modulated Mcl-1 levels in various glioblastoma cells tested, we examined whether knock-down of Mcl-1 would be sufficient to enhance apoptosis induced by ABT263." (PMID 27172899, 2016). "Taken together, downregulation of Mcl-1 could sensitize glioblastoma cells to or accelerate IR-induced apoptosis." (PMID 26775694, 2016). "USP9x expression correlated moderately but significantly with Mcl-1 expression in glioblastoma, supporting our hypothesis that USP9x stabilizes Mcl-1 in glioblastoma cells." (PMID 26775694, 2016). "To assess whether the WP1130-mediated down-regulation of Mcl-1 and Usp9X is due to a transcriptional mechanism we performed real-time PCR analyses in U251 glioblastoma cells following treatment with WP1130." (PMID 26872380, 2016). "Successful Mcl-1 knockdown in glioblastoma cells was verified by western blot." (PMID 26775694, 2016). "Furthermore, we examined four established (A172, U373, Ln229, T98G) and two primary (LKI, WKI) glioblastoma cell lines that differ in their ability to downregulate Mcl-1 and induce apoptosis in response to IR." (PMID 26775694, 2016). "Comparing human grade III astrocytoma with grade IV glioblastoma samples, we could show that Mcl-1 and USP9x are upregulated during tumor progression." (PMID 26775694, 2016). "Bcl-2 and the closely related Bcl-xL and Mcl-1 are often overexpressed in glioblastoma cells." (PMID 26775694, 2016).
glioblastoma (continued). "Moreover, Mcl-1 knockdown sensitized A172, Ln229, and T98G cells to IR-induced apoptosis, suggesting that Mcl-1 is an important factor increasing glioblastoma cell survival after irradiation." (PMID 26775694, 2016). "Although Mcl-1 knockdown by siRNA increased apoptosis induction after irradiation in all glioblastoma cell lines, USP9x knockdown significantly improved radiation-induced apoptosis in one of four cell lines and slightly increased apoptosis in another cell line." (PMID 26775694, 2016). "MCL-1 is overexpressed in human glioblastoma, which confers a survival advantage to tumor cells." (PMID 26036638, 2015). "Moreover, TIC10/ONC201 caused a down-regulation of the Hsp70 co-chaperone Bag3, which has been reported to mediate resistance to BH3-mimetics in glioblastoma by regulating Mcl-1 levels." (PMID 26474387, 2015). "In addition, in silico analysis based on the TCGA data set revealed a 5-fold overexpression of Mcl-1 mRNA in glioblastoma when compared to normal brain suggesting that Mcl-1 represents a valid target in this disease." (PMID 26008975, 2015). "CHX-induced Mcl-1 decline was also observed in glioblastoma and cervical cancer cells." (PMID 23402580, 2013). "Therefore, we used MCL-1 as a target for drug screening for the treatment of glioblastoma." (PMID 37538176, 2023). "Interestingly, in glioblastoma, somatic mutations in the PEST region of MCL-1 (D155G, D155H, and L174S) were shown to stabilize MCL-1; these mutations may participate in gliomagenesis." (PMID 37601693, 2023). "The authors observed that glioblastoma cells co-exposed to zotiraciclib and a pan-caspase inhibitor demonstrated only moderately weakened zotiraciclib-induced cytotoxicity, and zotiraciclib still suppressed phosphorylation of RNA Pol II and depleted MCL-1 protein levels." (PMID 34207158, 2021). "In contrast, Mcl-1 is a member of the anti-apoptotic fraction of Bcl-2 proteins, which has been shown to block therapeutic responses in glioblastoma (GBM), e.g., mediating radiation resistance." (PMID 32752193, 2020). "Through this analysis and in the context of a related pathway analysis (GREAT), we identified a super-enhancer around the Mcl-1 gene in glioblastoma, which was also identified in several other GBM cultures." (PMID 32752193, 2020). "However, the direct inhibition of Mcl-1 has several pitfalls, such as the fact that these molecules come with a high molecular weight, which, in the context of glioblastoma, might be cumbersome due to the presence of the blood brain barrier." (PMID 32752193, 2020). "To test our hypothesis that combined treatment with the Bcl-2 inhibitor ABT263 and the Mcl-1 inhibitor GX15-070 yields a more favorable antineoplastic activity in glioblastoma when compared to single-agent treatments, we first examined effects on cellular proliferation by MTT assays." (PMID 26008975, 2015). "In the present study, we showed that PD induces apoptosis in glioblastoma cells by downregulating MCL-1 expression and observed a strong predicted interaction between PD and MCL-1 in molecular docking analysis." (PMID 41049425, 2025). "In this study, we propose a novel therapeutic approach, demonstrating that PD exerts potent antitumor effects on glioblastoma cells by targeting LC3B and MCL-1 expression." (PMID 41049425, 2025). "In this study, we predicted the prognosis of glioblastoma patients, and therefore constructed MCL-1 related prognostic signature (MPS) and the development of MCL-1 small molecule inhibitors." (PMID 37538176, 2023). "Myeloid cell ischemia-1 (MCL-1), as a member of the B-cell lymphoma 2 (BCL-2) protein family, is one of the most frequently amplified genes in all human cancers including glioblastoma." (PMID 37538176, 2023). "High levels of Mcl-1 mediate BH3-mimetic resistance, suggesting that a dual inactivation of Bcl-2/Bcl-xL and Mcl-1 is necessary for apoptosis of glioblastoma cells." (PMID 34485282, 2021).